RET (ret proto-oncogene)
Diseases named in the same sentence as RET in open-access papers (continued):
Sharing a sentence is not in itself a finding about the gene and the disease.
tumor (continued). "Moreover, the RP3 cells are able to form tumour, once grafted in nude mice confirming the tumorigenic transformation of the immortalized NIH/3T3 cell line by RET/PTC3 oncogene." (PMID 24759995, 2014). "RET/PTC1 and RET/PTC3 in tumor cells were individually analyzed by RT-PCR." (PMID 24591770, 2014). "Interestingly, also a number of oncogenes is up regulated by E2 (MERTK, RET and its ligand ARTN), and several (putative) tumor suppressor genes are down regulated by E2 (BLNK, LATS2, RPRM) that are not, or less, regulated by EGF." (PMID 24758408, 2014). "When mice were treated with siRNA RET/PTC3-SQ NPs, tumour growth was strikingly inhibited compared to those receiving siRNA CT-SQ NPs, non-vectorized siRNA RET/PTC3 or saline solution (60% inhibition of tumoral volume compared to saline treated mice, LSD test, p<0.001)." (PMID 24759995, 2014). "Indeed, when FRTL (RET/PTC1) cells were transplanted into the subcutaneous tissue of nude mice, the resulting tumor cells retained 125I-uptake activity, as do some human papillary thyroid cancer tissues." (PMID 24014739, 2013). "Moreover, the dual inhibition of RET and FGFR combined with tyrosine kinase inhibitors resulted in greater suppressions of cell proliferation in vitro and tumor control in vivo than that which was achieved with either agent alone." (PMID 23509459, 2013). "Tumor/normal (T/N) ratio of RET/β actin mRNA level was not correlated with gender (male vs. female, P = 0.7636), age (age ≤65 vs. >65, P = 0.3204), and smoking status (smoker vs. nonsmoker, P = 0.6693)." (PMID 23342255, 2012). "The T/N ratio of RET/β actin mRNA level was not correlated with pathological stages, lymph node metastasis, tumor invasion statuses, and pathological subtypes (adeno-carcinoma vs. others, P = 0.2652)." (PMID 23342255, 2012). "Tumor/normal (T/N) ratio of RET/β actin mRNA levels was not different within gender, stage, smoking status, and pathological subtypes." (PMID 23342255, 2012). "In this context, we have successfully applied this approach using primary human thyrocytes expressing the thyroid-specific RET/PTC1 oncogene to model PTC, and we have demonstrated that RET/PTC1 regulates the expression of a distinct set of genes involved in inflammation and tumor invasion." (PMID 20877637, 2010). "In addition, tumor vascularization was evaluated by CD34 antigen staining in sections of tumors recovered from control and HB-19 treated RET mice." (PMID 20573279, 2010). "Clinical trials with several TKIs targeting RET, and to a lesser extent BRAF, and other TKRs have shown positive results, with about one-third of DeTC showing a reduction in tumor size up to 50%, with the longest treatment duration of approximately three-four years." (PMID 20628483, 2010). "The major somatic mutation (Met918Thr) localised in the tyrosine kinase domain in exon 16 of RET has been associated to a worse clinical outcome in sporadic MTC when compared with tumours that did not harbour this mutation." (PMID 19401695, 2009). "According to age, the Tg-E7 model evolved on a predominant goitrous mode with no tumour formation, whereas tumour formation occurred in 28% of the RET/PTC3 mice at 6 and 10 months." (PMID 18985036, 2008). "The association of cribriform tumour patterns and spindle cells is described in the columnar human PTC without any knowledge of the RET/PTC3 status, and in the morular/cribriform PTC." (PMID 18985036, 2008). "Targeting RET pathways may therefore provide a therapeutic strategy not only for malignancy but also for modulating the tumor microenvironment." (PMID 40282539, 2025). "Whether there is difference in RET protooncogene between the primary tumour, lymph node, and distant metastasis has not yet been investigated." (PMID 40729029, 2025). "Notably, no RAS or BRAF mutation or RET fusions (analyzed by intron baiting of select genes, including RET) were encountered in the PTC tumor." (PMID 40600748, 2025).
tumor (continued). "Based on the encouraging anti-tumor efficacy and favorable safety profiles, a pivotal phase 2 study has been initiated to further assess the efficacy and safety of SY-5007 at RP2D (160 mg BID) in patients with locally advanced or metastatic RET fusion-positive NSCLC (NCT05278364)." (PMID 39489747, 2024). "Molecular testing techniques available to detect RET rearrangement include next-generation sequencing (NGS), reverse transcription polymerase chain reaction (RT-PCR), fluorescence in situ hybridization (FISH), and immunohistochemistry, and the analysis of circulating tumor DNA (ctDNA)." (PMID 39882443, 2024). "Three RET NGS-positive cases were excluded for lack of tumor tissue after the previous analyses." (PMID 38525319, 2024). "In the tumour agnostic cohort, ORR was 57% (95% CI, 35–77%) and median duration of response, PFS and overall survival were 12 months, 7 months and 14 months, respectively, validating RET as a tissue-agnostic target for RET inhibition, which is crucial for precision medicine in cancer." (PMID 37207147, 2023). "BOS172738 demonstrated broad anti-tumor activity with an ORR of 33% (n = 18/54), an NSCLC ORR of 33% (n = 10/30), and MTC ORR of 44% (n = 7/16, including one complete response), and one patient with RET fusion–positive pancreatic cancer reported a partial response." (PMID 38201460, 2023). "Finally, the oncogenic RET kinase as well as CYP2W1 are direct PLAGL1/2 targets and may be potential drug targets in this tumor type, which should be top priorities for future functional validation." (PMID 36437415, 2023). "Responses were observed regardless of tumor type or RET fusion partner." (PMID 35962206, 2022). "Despite of this, we did not observe a very high expression correlation between DDR2 and RET in the R2 tumor datasets (not shown), which could suggest expression in different tumor cell subpopulations." (PMID 34716856, 2022). "LEN, a multikinase inhibitor of VEGF receptors 1-3, FGF receptors 1-4, platelet-derived growth factor receptor-a, RET, and KIT, could suppress tumor angiogenesis and antitumor immunity in tumor microenvironments, which would enhance the effect of PD-1 antibodies and TACE." (PMID 36212494, 2022). "In addition, GATA3, ERBB4, RET, NAT, and TFF3 genes are commonly expressed in tumor cells, which may also influence response to treatment." (PMID 36536751, 2022). "However, if a somatic driver RET mutation is detected, we can use this information in the therapeutic algorithm; a negative result is not necessarily informative of a RET negative status, in absence of tumor tissue data." (PMID 35422765, 2022). "Interestingly, aberrant RET signaling is not a driver event in all cell types, being involved in several additional mechanisms in the process of tumor genesis." (PMID 35422765, 2022). "Additionally, the mean tumor size was not significantly different (4.0 ± 2.0 vs. 4.6 ± 2.5 cm; P = 0.502), although those with RET-M918T were relatively younger by 8 years and had a tumor size that was approximately larger by 0.6 cm." (PMID 36704524, 2022). "In this phase 1/2 study of pralsetinib in patients with advanced or metastatic RET fusion–positive solid tumors, almost all of whom were previously treated with systemic therapy, pralsetinib showed robust and durable anti-tumor activity regardless of tumor type or RET fusion partner." (PMID 35962206, 2022). "Sorafenib, a novel multitargeted anticancer drug that targets RAF kinase, c-Kit and RET proto-oncogenes, VEGF receptor (VEGFR), and platelet-derived growth factor receptor (PDGFR), may exert its effects by arresting tumor cell cycles and by exerting anti-vascular effects." (PMID 36612173, 2022). "Thus, fusions in ROS1, RET, NTRK1 and amplifications in MET, ALK, EGFR, for example, may not be detected with circulating DNA and RNA, notably during tumor progression under treatment with TKI targeting ALK rearrangements." (PMID 33467720, 2021).
tumor (continued). "As follows from the results, except for RET/PTC3, none of the oncogenes or unknown drivers were associated with aggressive tumor features." (PMID 34282777, 2021). "Tumour testing is still required if a RET alteration is not detected in a LB." (PMID 34915883, 2021). "However, some actionable targets can be present in other genes (notably MET, RET, NTRK, and HER2), allowing inclusion into clinical trials of patients with EGFR, ALK, ROS1, and BRAF wild-type tumors with less than 50% PD-L1-positive tumor cells." (PMID 32294880, 2020). "Although there is no robust evidence linking RAS mutations and tumor behavior or prognosis, there are some data suggesting RAS-mutated sMTC may have a less aggressive clinical course than RET-mutated sMTC." (PMID 32668761, 2020). "Additionally, the mutation-carrier relatives whose neoplasm diagnoses were made after RET screening were younger than the patients whose neoplasm diagnoses were made before genetic analysis (not significant)." (PMID 30624503, 2018). "To deeper investigate phenotypic differences in RET/PTC1TG mice carrying one, two, or no Patz1-null alleles, we analyzed expression of Ki-67 (a typical marker of cell proliferation) by immunohistochemistry on tumor samples from each genotypic group." (PMID 29584698, 2018). "By serial dilutions with the tumor sample 28, which is negative for RET and TRK rearrangements, we demonstrated that the PTC-MA assay is able to detect the presence of fusion genes with high sensitivity, also when they were present in 5% only of the total cDNA." (PMID 29214440, 2018). "In addition to the RET, the superexpression of receptors 2 and 3 of the vascular endothelial growth factor (VEGF), which leads to tumor angiogenesis and nutrition, and of the epidermal growth factor receptor (EGFR), involved in tumor proliferation, also contributes to the pathogenesis of MTC." (PMID 28658345, 2017). "In other words, some of the ReT positivity may have been due to tumor nature rather than UE procedure itself." (PMID 26929181, 2016). "Notably, apart from constitutive activation of the mitogen-activated protein kinase signaling pathway (driven by mutant RET), the mechanisms of MTC tumor development and progression are largely unknown." (PMID 26395490, 2015). "In addition to the lack of evidence regarding a ‘driver’ property of RET Y791F in human tumours, two reports describing results indicative of a ‘passenger’ role for Y791F." (PMID 25425582, 2015). "For example, sunitinib inhibits a number of growth factor receptors regulating both tumor cell proliferation/survival and tumor angiogenesis including vascular endothelial growth factor receptors, platelet-derived growth factor receptors α and β, c-Kit, FLT3, CSF1R, and RET." (PMID 24701565, 2014). "Cabozantinib has better effects on tumor angiogenesis and survival than those found with combinations of selective inhibitors of MET and VEGF signaling in the same model, suggesting that AXL or other targets (such as RET, KIT and TIE2) contribute to the efficacy of cabozantinib." (PMID 24213559, 2013). "Thus, our data demonstrate that RET/GFRα signals are dispensable for thymic T cell development in vivo, indicating that pharmacological targeting of RET signalling in tumours is not likely to result in T cell production failure." (PMID 23300832, 2012). "Interestingly, in each case, the RET fusion remained suppressed on treatment raising the possibility multiple tumor clones with distinct drivers (either RET or KRAS) might co-exist at the baseline and behave differently under selective pressure of RET inhibition." (PMID 39655713, 2025). "This case highlights a potential therapeutic role for RET inhibitors even in the absence of canonical fusions, and underscores the importance of reassessing the tumor’s molecular profile following treatment failure, as acquired genomic alterations may provide new targets for precision therapy." (PMID 40606448, 2025).
tumor (continued). "Also, the vandetanib administration reduced tumors but could not induce tumor regression in models not expressing EGFR or RET." (PMID 38892472, 2024). "In addition, CBLC may not always lead to the destabilization of RET, but cause exactly the opposite in the absence of an interacting protein, CD2AP, thereby potentially also stimulating tumor formation." (PMID 38045004, 2023). "Moreover, patients with positive lymph node also had the larger tumor represented by the tumor diameter than those with negative lymph node ones (≥1 cm: 95.9% vs. 90.1%, p = 0.0396), as well as the presence of RET genetic alteration (7.3% vs. 1.7%, p = 0.0208)." (PMID 37081757, 2023). "Tumor regressions were seen in nearly all (RET-mutated) patients receiving selpercatinib (LIBRETTO-001 trial), regardless of the kind of RET mutation or whether the participant had or had not received previous TKI treatment with cabozantinib, vandetanib, or both." (PMID 36768635, 2023). "Of interest, calcitonin levels decreased dramatically after vandetanib therapy, but the marker decrease did not directly correlate with changes in tumor volume; thus, calcitonin may not be a reliable marker of tumor response in patients receiving RET inhibitor therapy." (PMID 37979019, 2023). "Thus, in patients with negative or not known RET status, the combination therapy bortezomib/vandetanib might impact on the duration of tumour response, by decreasing the rate of escape observed in MTC patients initially responding to vandetanib." (PMID 37152939, 2023). "Notably, although the majority of acquired RET fusions were detected by circulating nucleic acid method using plasma ctDNA, 4 out of 49 patients in the refined cohort contributed only FFPE samples, raising a concern of missing rare fusions compared to tumor-based comprehensive genomic profiling." (PMID 36059009, 2022). "Additionally, regorafenib targets the RET-Src signaling axis to inhibit JAK1/2-STAT1 and MAPK signaling and concurrently inhibits PD-L1 expression, suggesting inhibition of RET-Src axis may impact immune response to tumor cells in vivo." (PMID 35957881, 2022). "Many authors hypothesize that RET/PTC rearrangements are important for the initiation of the tumor, but are not necessary for its further progression, as RET/PTC rearrangements are frequently found in microcarcinomas, in thyroid adenomas and non neoplastic lesions." (PMID 25789503, 2015). "Although, both oncoproteins, BRAF V600E and RET/PTC1, share common property of signaling via activation of MEK-ERK kinase pathway, they have unique phenotypic features, signifying that the different tumor biology may characterize cancers arising from different oncogenes." (PMID 24797369, 2014). "The different results for these two cancer subtypes may reflect the smaller number of FTC patients, which reduced the power of the analysis, or may reflect the differences in the aetiology of these tumours, since alterations of the RET signalling pathway are commonly found in PTC, but not FTC." (PMID 25330015, 2014). "Over the past 5 years, the EMA has approved several of these effective treatments based on specific alterations, regardless of the tumor type, such as larotrectinib and entrectinib for NTRK fusions and selpercatinib for RET fusions." (PMID 41197434, 2025). "Furthermore, although RET point mutation co-occurs with BRAF V600E mutation, the mutation abundance of BRAF V600E was significantly lower than that of RET point mutation, suggesting that a large proportion of tumor cells have only RET point mutation but no BRAF V600E mutation." (PMID 38734621, 2024). "RET was the most abundant of these kinases in non-tumorous tissues (~35%), while PGFRB was the most abundant RTK in tumours (~47%)." (PMID 36890818, 2023).
tumor (continued). "Moreover, we also found that patients with positive lymph node also had the larger tumor represented by the tumor diameter than those with negative lymph node ones (≥1 cm: 40.7% vs. 25.7%, p = 9.197e‐05), as well as the presence of RET genetic alteration (16.3% vs. 2.7%, p = 2.566e‐03)." (PMID 37081757, 2023). "In addition, we found that the GDNF-GFRA1 axis protects tumor cells from apoptosis under metabolic stress via regulating lysosomal functions and autophagy flux, and participates in the regulation of cytosolic calcium ion signalling in a RET-independent and non-canonical way." (PMID 36808605, 2023). "Further targeted systemic therapy is limited to non-resectable advanced stage patients with tumor genetic alterations such as ALK (anaplastic lymphoma kinase), MET (Met proto-oncogene), RET Ret proto-oncogene), and ROS1 (c-ROS proto-oncogene 1)." (PMID 35448189, 2022). "Using GEPIA, we discovered that the levels of RET and FN1 in tumor tissues were much higher than those in normal tissues." (PMID 36601474, 2022). "One study observed that PET-based radiomics combined with tumor stage and age was able to differentiate ALK/ROS1/RET fusion-positive and fusion negative tumors (sensitivity = 0.73, specificity = 0.70)." (PMID 34208595, 2021). "Adjusted, using all available baseline covariates, and unadjusted analyses were conducted to compare tumor response, PFS and OS between patients with RET-fusion positive and RET-fusion negative disease as detected by next-generation sequencing." (PMID 33402119, 2021). "All these FGFR inhibitors are multi-kinase inhibitors that also exhibit nonspecific anti-tumor activities against other tyrosine kinases, including VEGFR, PDGFR, ROS1, and/or RET." (PMID 33710807, 2021). "The frequency of RET/PTC3 is lower in sporadic PTC, even from young children, and other types of activated oncogenes do not seem to confer very high tumor aggressiveness in young patients." (PMID 34885148, 2021). "RET/PTC1 and BRAFV600E did not confer tumor aggressiveness, in agreement with previous reports on the lack of overly aggressive features in BRAFV600E-positive PTCs in pediatric patients." (PMID 34282777, 2021). "Together, these data suggest that cabozantinib inhibits SCNPC tumor growth in vivo irrespective of tumor MET and RET status." (PMID 33471819, 2021). "Copy number variations (CNV) of the RET gene have been described in 30% of Medullary Thyroid Cancer (MTC), but no information is available about their role in this tumor." (PMID 33383911, 2020). "Our analysis showed the presence of a higher number of copies of the RET gene and hinted for a retrocopy insertion in MTC carcinoma cell lines and MTC tumor tissues, which are lacking in patient-matched blood and normal thyroid samples." (PMID 31288802, 2019). "After 2 months, tumor formation was evident at the site of FRTL (RET/PTC1) cell injection in six of ten mice, but one mouse did not have a tumor form at the site of FRTL (pcDNA) cell injection." (PMID 24014739, 2013). "Tumor formation in these selected MEN 2A-related MTCs may have occurred by first, a RET germline mutation, leading to hyperplasia of C cells and second, an amplification event of mutant RET which, however, could not be consistently detected by the methods used by us (polymorphic marker analysis)." (PMID 16707008, 2006). "However, tumours within Cluster 2 (NF1, RET or HRAS) had no differentially methylated probes in any comparisons between this group." (PMID 38124114, 2023). "Interestingly, RET/Src signaling showed no influence on MHC-I levels, while suppression of RET/Src signaling by regorafenib reduced IFN-γ-induced expression of PD-L1 and IDO1 on tumor cells." (PMID 36119072, 2022). "Finally, RET fusions have been found in a small fraction of patients with CRC (<1%), predominantly on the right side, RAS and BRAF wild-type tumours, and carry a worse prognosis compared to patients without RET fusions." (PMID 35207616, 2022).